OR5AC1 (olfactory receptor family 5 subfamily AC member 1 (gene/pseudogene))
Description:
Odorant receptor.
Synonyms: OR5AC1P
Gene: Protein-coding gene on chromosome 3 (98,064,472 to 98,065,396, forward strand). Ensembl gene ENSG00000213439.
Subcellular location: Cell membrane
Pathways (Reactome):
Sensory Perception: Expression and translocation of olfactory receptors
Homologues: Paralogues in human: OR5H6 (32% identical), OR5AC2 (32% identical), OR5H1 (31% identical), OR5H14 (31% identical), OR5H15 (31% identical), OR5H2 (31% identical), OR5H8 (31% identical), OR5K1 (30% identical), OR5K3 (30% identical), OR5K4 (30% identical), OR5K2 (29% identical), OR5AP2 (27% identical), and 84 more.